CFTR (CF transmembrane conductance regulator)
Diseases named in the same sentence as CFTR in open-access papers (continued):
Sharing a sentence is not in itself a finding about the gene and the disease.
acute pancreatitis (19 papers, 2008 to 2026). An acute inflammatory process that leads to necrosis of the pancreatic parenchyma. "Among 12,082 women tested, CFTR carriers (n = 451) were at significantly higher risk of developing acute pancreatitis (p = 3.93 × 10−6; OR = 4.68 [2.43–9.00])." (PMID 40468859, 2025). "Acute pancreatitis is typically seen in people with heterozygous CFTR mutations or milder variants with preserved pancreatic function." (PMID 37958749, 2023). "In conclusion, our results confirm that impairment of CFTR function increases the susceptibility of the pancreas towards exogenous injury and clearly renders the disease course of acute pancreatitis more severe." (PMID 33682322, 2021). "Acute pancreatitis is uncommon in PwCF due to the widespread destruction of the exocrine pancreas in utero as early as the seventeenth week of gestation, especially in homozygous variants of the CFTR mutation." (PMID 37958749, 2023). "Two of them had recurrent acute pancreatitis due to SPINK and CFTR mutation, respectively, the third child had obstructed choledochal cyst with biliary pancreatitis, the fourth child was found to have the long common channel and the last had sodium valproate induced acute pancreatitis." (PMID 34927163, 2022). "Acute pancreatitis was rare in the cohort, with a prevalence of 2.44% among CFTR carriers and 0.63% among controls." (PMID 40468859, 2025). "In this case series we report the potential genotype-phenotype correlations with the novel R248G CFTR mutation: CUAVD in males, reduced female fertility, and recurrent acute pancreatitis." (PMID 28196530, 2017). "Mutations in SPINK 1, CFTR and CTRC were detected in 6.3 %, 2.3 % and 1.8 % of patients with acute pancreatitis versus 3.2 %, 3.8 % and 1.2 % of volunteers in the control group." (PMID 26100556, 2015). "The aim of this study was to determine the frequency of genetic mutations in SPINK1, CFTR and CTRC genes in patients with acute pancreatitis (AP), as well as to investigate their relation with the etiology and clinical course." (PMID 26100556, 2015). "One study has suggested a link between CFTR dysfunction and recurrent acute pancreatitis in patients with pancreas divisum." (PMID 18501000, 2008). "To investigate whether a modified CFTR expression alters disease severity, we induced acute pancreatitis in CFTRtm1HGU mice and corresponding wild‐type animals by repeated intraperitoneal caerulein injections." (PMID 33682322, 2021).
fibrosis (18 papers, 2012 to 2025). the formation of excess fibrous connective tissue in an organ or tissue in a reparative or reactive process. "Mutations within CFTR’snucleotide-binding domains (NBDs) disrupt this process, leading tocystic fibrosis." (PMID 41358137, 2025). "The Cystic Fibrosis Conductance Transmembrane Regulator gene encodes for the CFTR ion channel, which is responsible for the transport of chloride and bicarbonate across the plasma membrane." (PMID 38928073, 2024). "Used to treat fibrosis in patients having homozygous F508del mutation in their CFTR gene." (PMID 34803446, 2021). "We then tested SNIPRs with the lacZ reporter gene targeted to the cystic fibrosis CFTR ΔF508 mutation to determine if a paper-based colorimetric assay could be implemented." (PMID 32109416, 2020). "In the current study, LSM confirmed CFLD at baseline and demonstrated significant regression of fibrosis at the end of follow-up after long-term CFTR modulator therapy." (PMID 41465734, 2025). "Given that the accumulation of misfolded proteins is a contributing factor to numerous diseases, including cystic fibrosis (CFTR), Parkinson’s disease (a-synuclein), and Alzheimer’s disease (β-amyloid), we utilized A549 (alveolar basal epithelial) and SH-SY5Y (neuroblastoma) cells as models." (PMID 41303334, 2025). "They suggested the cause to be previous vasectomy in 2 cases and cystic fibrosis (CFTR) mutations and congenital bilateral absence of the vas deferens (CBAVD) in the other 2 men." (PMID 29090218, 2017). "In ALIs grown from donors with and withoutCystic Fibrosis, we noted greater pH variability in Cystic FibrosisALIs compared to healthy ALIs suggesting that apical pH may not simplybe a surrogate measurement of CFTR function." (PMID 38659220, 2024). "Consistently, we have previously proposed that successful CFTR modulator drugs need to address not just the rescue of CFTR-mediated ion transport, but also CFTR protective role against EMT to protect individuals with CF from fibrosis and cancer propensity." (PMID 35500936, 2022).
autosomal dominant polycystic kidney disease (17 papers, 2015 to 2025). Autosomal dominant form of polycystic kidney disease. "Diseases like cystic fibrosis, secretory diarrhea, or autosomal dominant polycystic kidney disease are linked to CFTR mutations." (PMID 40568930, 2025). "Hyperactivation of the cystic fibrosis transmembrane conductance regulator (CFTR) contributes to secretory diarrhea, a major cause of pediatric mortality worldwide, and autosomal dominant polycystic kidney disease (ADPKD), the most common inherited cause of end-stage renal disease." (PMID 40750590, 2025). "Increased chloride secretion due to enhanced CFTR activity is associated with pathologies such as cholera-induced enterotoxigenesis diarrhoea, autosomal dominant polycystic kidney disease (ADPKD), which presents with enlarged cysts, and hyperchloremia due to kidney dysfunction." (PMID 35997536, 2022). "Cystic fibrosis transmembrane conductance regulator (CFTR) inhibitors, including CFTRinh-172, have been developed as therapeutic candidates to treat secretory diarrhea and autosomal dominant polycystic kidney disease." (PMID 38422021, 2024). "While activation of CFTR is vital to treating cystic fibrosis, selective inhibition of CFTR is a potential therapeutic strategy for secretory diarrhea and autosomal dominant polycystic kidney disease." (PMID 38422021, 2024). "cAMP-stimulated cell proliferation and CFTR-dependent Cl− secretion play a decisive role for epithelial cyst enlargement in autosomal dominant polycystic kidney disease (ADPKD)." (PMID 30404151, 2018). "Yet, this discovery may open the way to new therapeutic opportunity for diseases with an abnormal increased activity of CFTR channel like autosomal dominant polycystic kidney disease." (PMID 40568930, 2025). "With more clinical focus regarding CFTR in autosomal dominant polycystic kidney disease (ADPKD), the importance of CFTR in fibrosis is increasingly recognized." (PMID 36277193, 2022). "Hyperactivation of the cystic fibrosis transmembrane conductance regulator (CFTR) is central to the pathogenesis of secretory diarrheas and autosomal dominant polycystic kidney disease (ADPKD)." (PMID 40750590, 2025). "In autosomal dominant polycystic kidney disease (ADPKD), the main mechanism mediating Cl− secretion into cysts is via the cystic fibrosis transmembrane conductance regulator (CFTR) in principal cells." (PMID 39334956, 2024).
emphysema (17 papers, 2009 to 2025). "To investigate the mechanism underlying SphK2-mediated pulmonary emphysema, remodeling, and inflammation, we analyzed the effect of SphK2 deficiency on protein expression of CFTR." (PMID 36226596, 2023). "Another important mechanism which plays a crucial pathogenic role in both CF and COPD-emphysema is ceramide accumulation, and numerous studies have highlighted that a loss or decrease in CFTR and/or CS exposure leads to an increase in ceramide levels." (PMID 32847034, 2020). "Recent studies shows that CFTR protein expression correlates inversely with emphysema severity in lungs of COPD patients, suggesting that impaired CFTR function may also be implicated in emphysema formation in humans." (PMID 29849481, 2018). "Furthermore, it has been reported that CS-induced CFTR dysfunction and the associated inflammatory/oxidative stress cause an impairment of autophagy that also contributes to the development of emphysema." (PMID 29849481, 2018). "Hence, future longitudinal studies in larger patient cohorts are necessary to determine the impact of different classes of CFTR mutations, differences in treatment regimens and adherence to therapy, as well as other environmental and genetic factors on emphysema in patients with CF." (PMID 23991177, 2013). "On the other hand in patients with emphysema, there is a correlation between the spirometric values of lung function and CFTR, Interestingly, a recent murine model shows the contribution of a reduced expression of CFTR and airspace enlargement." (PMID 34680554, 2021). "Our relatively recent study using GSNO, an endogenously occurring nitric oxide donor, highlights the biological significance of CS-induced CFTR dysfunction-related autophagy impairment in mediating COPD-emphysema pathogenesis." (PMID 32847034, 2020). "Supporting studies demonstrate that autophagy augmentation restores CS-induced CFTR dysfunction, inflammatory-oxidative stress, ceramide accumulation, and COPD-emphysema pathogenesis by rescuing aggresome-bound mutant ΔF508-CFTR to the plasma membrane (PM)." (PMID 32847034, 2020). "Their results revealed an inverse correlation between the expression of CFTR and severity of emphysema and ceramide accumulation in COPD patients compared with healthy subjects." (PMID 29849907, 2018). "In humans, the abundance of CFTR protein in the lung tissue of patients with pulmonary emphysema was strikingly correlated with lung function (FEV1 and FVC) and inversely correlated with their COPD stages." (PMID 29849907, 2018). "Our data strongly suggest that functional regulation of CFTR was critically involved in SphK2/S1P signaling-mediated pulmonary fibrosis and inflammation, and CFTR dysfunction has a close link to SphK2/S1P activation-mediated airways remodeling and emphysema after long-term CS exposure." (PMID 36226596, 2023). "However, the potential role of SphK2 in regulating the CFTR function and CS-induced pulmonary fibrosis and emphysema remained unclear." (PMID 36226596, 2023). "Furthermore, a sustained reduction of CFTR protein expression was found to correlate with the smoke-induced emphysema in mice with different genetic backgrounds (C57BL/6, ApoE2/2, A/J, CD1, and Nrf22/2)." (PMID 29849907, 2018). "A role of CFTR dysfunction in the pathogenesis of emphysema is further supported by studies in βENaC transgenic mice demonstrating that CF-like airway surface dehydration does cause not only chronic mucus obstruction and airway inflammation but also emphysematous changes in these mice." (PMID 29849481, 2018). "Further studies demonstrated that the CFTR-dependent lipid rafts and ceramide signaling played a modulatory role in CS-induced lung epithelial injury and emphysema, indicating that membrane CFTR was essential for regulating lipid raft ceramide accumulation and inflammatory signaling." (PMID 29849907, 2018).
emphysema (continued). "These proof-of-concept studies may facilitate future clinical trials that will be required to determine therapeutic effects improving CFTR function and airway surface hydration on mucus obstruction, airway inflammation and emphysema in patients with COPD." (PMID 26066648, 2015). "We speculate that CFTR dysfunction may trigger several of these mechanisms and thereby induce emphysema formation in patients with CF." (PMID 23991177, 2013). "Several mechanisms mainly related to CFTR dysfunction may induce emphysema formation in CF patients; among these, chronic inflammation with protease/antiprotease imbalance and extracellular matrix proteolysis, altered ceramide metabolism, alveolar apoptosis, and defective autophagy." (PMID 29849481, 2018). "Conversely, restoring CFTR levels by S-nitrosoglutathione (GSNO) augmentation corrects CS-induced autophagy dysfunction, inflammatory-oxidative stress and COPD-emphysema features." (PMID 32847034, 2020). "With the prolongation of CS exposure time, mice lacking CFTR developed alveolar remodeling similar to emphysema." (PMID 36226596, 2023). "Hence, we propose that restoration of m-/r- CFTR expression may be a promising therapeutic strategy to combat SHS impaired bacterial phagocytosis to control chronic infection and inflammation in COPD-emphysema subjects." (PMID 25794013, 2015). "Our earlier studies described a direct correlation between a lack of lipid-raft CFTR expression and CS-induced apoptosis along with defective autophagy and the progression of COPD-emphysema via ceramide or lactosylceramide accumulation." (PMID 32847034, 2020).
Obesity (17 papers, 2019 to 2026). Accumulation of substantial excess body fat. "The association between obesity and milder CFTR mutations, along with the intriguing link between CFTR modulator use and weight gain, enriches our understanding of CF pathophysiology." (PMID 38999218, 2024). "With regard to the effect of genotypes, those carrying at least one allele with a CFTR mutation with residual function (RF) displayed overweight at 24.8% and obesity at 7.5%." (PMID 38999218, 2024). "There is an increasing prevalence of overweight and obesity among individuals with CF, even among individuals with CF who are pancreatic insufficient and who have severe CFTR mutations." (PMID 37799765, 2023). "Patients using CFTR modulator therapies have a favorable evolution of CF but present an increased risk for obesity." (PMID 36678185, 2023). "In PwCF, overweight and obesity have traditionally been associated with factors consistent with more mild disease, including CFTR genotype associated with pancreatic sufficiency or mild CFTR dysfunction, higher FEV1pp, older age, and fewer pulmonary exacerbations." (PMID 40806116, 2025). "Patient factors associated with increased obesity incidence included age older than 45 years, male gender, pancreatic sufficiency, possession of at least one CFTR variant conferring residual function, ppFEV1 > 90, and lower prevalence of Pseudomonas aeruginosa colonization." (PMID 38999218, 2024). "With rapidly expanding access to CFTR modulators, longer life-spans, and increasing obesity, people with CF may be at risk of serious cardiovascular complications in the near future." (PMID 34868883, 2021). "The widespread use of CFTR modulators has dramatically changed the nutritional status of pwCF, leading to a higher prevalence of overweight and obesity." (PMID 41440516, 2025). "With CFTR modulator therapies, there has been an increase in the prevalence of overweight and obesity in pwCF." (PMID 39599743, 2024). "The accelerated growth of overweight and obesity in PwCF observed in recent years (3.5% increase per annum - 2018–2020; 1.1% increase per annum - 2000–2020), has coincided with an increased use of CFTR modulator therapy." (PMID 36091185, 2022). "The advancements in gene therapy and the subsequent introduction of CFTR modulator therapy to treat PwCF, has resulted in increased rates of overweight and obesity, highlighting it is now prudent to establish an alternative diet for PwCF." (PMID 36091185, 2022). "There is limited evidence on the optimal diet for PwCF, especially in the setting of new highly effective CFTR modulators and the development of overweight and obesity in this population." (PMID 35334873, 2022). "The use of CFTR modulator therapies has resulted in the emergence of overweight and obesity, which will undoubtedly become a more frequent feature in CF." (PMID 36091185, 2022). "More studies of longer duration are needed to examine body composition and fat distribution changes on CFTR modulators in the setting of unintended weight gain and the development of overweight and obesity on these drugs." (PMID 35334873, 2022). "As people with CF become more physiologically similar to the general population with the advent of CFTR modulator therapies, the factors driving obesity in the general population may become increasingly relevant to people with CF." (PMID 34868883, 2021). "Whether reducing CFTR function contributes to delayed wound healing in obesity remains to be determined." (PMID 32826922, 2020). "However, overweight and obesity have emerged as an important issue in the CF population due to advancements in therapy and increased longevity, especially in recent years with the introduction of CF transmembrane conductance regulator (CFTR) modulator therapies." (PMID 35334873, 2022). "Among younger subjects, subgroups with higher rates of overweight and obesity were characterized by ppFEV1 exceeding 90%, the absence of PERT, and the presence of RF CFTR mutations in the genotype." (PMID 38999218, 2024).
Obesity (continued). "Furthermore, from 2018 to 2020, there was an increase of 7.0% in overweight and obesity cases in PwCF, highlighting the acceleration in recent years within this population, coinciding with increases in the use of CFTR modulator therapy." (PMID 36091185, 2022). "As life expectancy continues to increase in this population with the use of CFTR modulators, non-traditional nutrition issues have emerged, and overweight/obesity have become areas of interest in CF clinical care and research." (PMID 35334873, 2022).
Secretory diarrhea (17 papers, 2006 to 2025). Watery voluminous diarrhea resulting from an imbalance between ion and water secretion and absorption. "CFTR inhibitors have been proposed to treat secretory diarrhoea, a major cause of infant mortality in developing countries as well as being a frequent complication of cancer drug treatments." (PMID 36545778, 2023). "CF and secretory diarrhea are two major human diseases associated with dysregulated CFTR channel activities." (PMID 28869532, 2017). "Several human diseases are associated with altered channel function of CFTR, including CF and secretory diarrhea." (PMID 28869532, 2017). "In summary, nornidulin is identified as a novel inhibitor of CFTR Cl- channels possibly by mechanisms involving direct inhibition and intracellular cAMP reduction, which is involved in the pathogenesis of secretory diarrheas." (PMID 39715175, 2024). "We also explore the possibilities of targeting this complex to fine tune CFTR channel activity, with a hope to open up new avenues to develop novel therapies for CF and secretory diarrhea." (PMID 28869532, 2017). "Here, we identified a widely used Thai herbal remedy, Krisanaklan, as having broad antidiarrheal efficacy in bacterial and viral models of secretory diarrhea, which, at the cellular level, inhibits the two major enterocyte Cl− channels, CFTR and CaCC." (PMID 24551253, 2014). "Our laboratory has identified, by high-throughput screening, several classes of small-molecule CFTR and CaCC inhibitors, and has shown their efficacy in mouse models of secretory diarrheas." (PMID 24551253, 2014). "It has been postulated that CFTR protein mediates toxin-induced secretory diarrhoea and that heterozygotes, having a less functional CFTR, were protected from dehydration due to diarrheal diseases caused by toxins of Vibrio cholera and Escherichia coli." (PMID 24204804, 2013). "EGCG and ECG could be new lead compounds for development of CFTR-related diseases such as secretory diarrhea." (PMID 25747701, 2015). "EGCG and ECG could be new lead compounds for developing therapeutics of CFTR-related diseases such as secretory diarrhea and polycystic kidney disease." (PMID 25747701, 2015). "CFTR is a well-validated target for development of inhibitors for therapy of secretory diarrheas." (PMID 25747701, 2015). "The cystic fibrosis transmembrane conductance regulator (CFTR), a cAMP-dependent Cl- channel localized to the luminal membrane of enterocytes, is proposed as a promising therapeutic target for secretory diarrheas." (PMID 36490300, 2022).